TLR2 (toll like receptor 2)
Diseases named in the same sentence as TLR2 in open-access papers (continued):
Sharing a sentence is not in itself a finding about the gene and the disease.
asthma (continued). "Analysis of the genotypes adjusted by gender also resulted in significant associations of TLR2 +596 genotypes and asthma in the Puerto Rican population." (PMID 27495363, 2016). "For instance, a placebo-controlled intervention study conducted in 916 children from the Netherlands reported that TLR2 variants influenced the susceptibility of developing asthma in response to NO2 and PM2.5 exposure." (PMID 24602767, 2014). "Toll-like receptor 2 (TLR2), for instance, has been shown to affect the risk of asthma and atopy in farmers, and CD14 appears to modify the effect of farm milk on allergic disease." (PMID 24260339, 2013). "Single nucleotide polymorphisms (SNPs) in the TLR2 gene that led to decreased mRNA expression were positively associated with asthma susceptibility." (PMID 23781124, 2013). "In our study, we specifically show that expansion of lung Treg cells via TLR-2 activation at the time of allergen challenge is associated with long-term protection against asthma manifestations in the mouse." (PMID 23393567, 2013). "Genetic variation in TLR2 (rs4696480) has been identified as a major determinant of the susceptibility to asthma and allergies in children of farmers." (PMID 22272212, 2012). "TLR-2 is of particular interest since genetic variation in TLR2 is a major determinant of the susceptibility to asthma and allergies in children." (PMID 18315832, 2008). "The elevated expression of TLR4 and TLR1/TLR2 induced by type-2 cytokines is assumed to modulate the impact of bacterial infections on Th2 associated pulmonary diseases like asthma." (PMID 16316467, 2005). "Polymorphisms in the TLR2-encoding gene are associated with the risk of asthma development." (PMID 36636604, 2023). "Additionally, a polymorphism in the TLR2 gene was shown to be associated with the risk of asthma development, while another TLR2 polymorphism had a protecting effect." (PMID 37759430, 2023). "TLR2-16934 A > T polymorphism may be a genetic predictor of the coexistence of asthma, atopic conjunctivitis, and family history of atopic disease in patients with AD, especially in subjects with higher IgE." (PMID 36465933, 2022). "The present study showed that overexpression of miR‐224 could inhibit the inflammation caused by PM2.5 by targeting TLR2 specifically, which suggested that miR‐224 may act as an inhibitor against the development of asthma." (PMID 31978265, 2020). "However, the TLR2–urease interaction has been associated with the generation of immune tolerance responses through the activation of Treg cells in a murine asthma model." (PMID 31185594, 2019). "TLR2-deficient mice exhibited significantly milder clinical symptoms (semi-quantitative scoring 1 (0~1)), which was slightly lower than that of the wild-type group with asthma (P = 0.056)." (PMID 28094276, 2017). "The TLR2 +596C/T variant was related to lower asthma risk in a French population." (PMID 27495363, 2016). "In addition to TLR4, variants of the TLR2 gene were reported to have some association with childhood asthma in Caucasians, and TLR2 polymorphism affects the asthma risk and lung function." (PMID 27274620, 2016). "Our study demonstrates an association between the TLR2 +596 SNP and asthma in Puerto Ricans." (PMID 27495363, 2016). "The genotype of the TT variant of the homozygous polymorphism rs7656411 in TLR2 may reduce the incidence of asthma." (PMID 26617525, 2015). "In addition to TLR4, polymorphisms present in the TLR2 gene are also associated with the risk of asthma development and overall lung function." (PMID 26617525, 2015). "The enhanced propensity of individuals with the P22L mutation to develop asthma is in line with the observed decreased capacity of IRAK-M with mutations in this region (P22A-A23S mutant) to down-regulate IL-6 expression in macrophages upon TLR2/4 stimulation." (PMID 25481771, 2014).
asthma (continued). "Previous human studies have demonstrated that decreased TLR2 mRNA expression and receptor function due to SNPs in the TLR2 gene are positively associated with asthma susceptibility, and high-atopic-risk infants have been reported to have low TLR2 expression on their cord blood CD34 (+) cells." (PMID 23781124, 2013). "Genetic polymorphisms in TLR2 may decrease the risk of asthma and atopy in children exposed to farming environments, where microbial exposures are high." (PMID 22151743, 2011). "Also, genetic variation in TLR2 was described to be a major determinant of the susceptibility to asthma and allergies in children of farmers." (PMID 16551363, 2006). "Notably, the results of studies on TLR2 SNPs and the risk of asthma in different populations are contradictory, and meta-analyses suggest that other SNPs, such as rs4696480 and rs3804099, are associated with asthma." (PMID 37426425, 2023). "Furthermore, TLR2 gene variants act as determining factors in asthma development." (PMID 36636604, 2023). "TLR2 deletion blocks the development of asthma, but cannot block the proinflammatory effect caused by B7-H3, which suggest the B7-H3–mediated effects observed in the present study are independent of TLR2 signaling, at least, not only depends on the TLR2 signaling." (PMID 28094276, 2017). "For instance, TLR2 regulates allergic airway inflammation through the PI3K/Akt signaling pathway, which is associated with autophagy in asthma models." (PMID 40598285, 2025). "Nevertheless, this is complicated by the fact that TLR2 drives a type 1 deviation during the chronic phase of atopic dermatitis, contrasting with generally type 2-polarized immune response of asthma." (PMID 40672946, 2025). "Findings from previous studies indicated reduced levels of inflammatory markers in TLR2 knockout mice, suggesting the involvement of these pathways in asthma." (PMID 40598285, 2025). "In conclusion, the TLR2/TLR6 agonist FSL-1 administered in the lungs by nasal instillation after the establishment of experimental asthma significantly decreased AHR and eosinophilia." (PMID 39273551, 2024). "In OVA sensitized mice, a long-term protection from asthma was sustained by TLR2-induced Treg proliferation." (PMID 37426425, 2023). "The role of TLR2 in the asthmatic mouse model and its possible mechanism of action were observed, thereby providing new insights into the pathogenesis of asthma and identifying new possible targets for asthma prevention and treatment." (PMID 36706056, 2023). "The role of TLR2 in an asthmatic mouse model and its possible mechanism of action were assessed to provide new insights into the pathogenesis of asthma and identify new possible targets for its prevention and treatment." (PMID 36706056, 2023). "Single nucleotide polymorphisms (SNP) in five different TLRs (TLR2, TLR4, TLR6, TLR9, TLR10) were described to significantly contribute to asthma susceptibility, severity, and responsiveness." (PMID 37759430, 2023). "rs3804099 in TLR2 and rs4986791 in TLR4 are significantly associated with an increased risk of asthma." (PMID 35911120, 2022). "Toll-like receptors (TLRs) such as TLR4 and TLR2 are important for the adaptive Th2-cytokine-driven inflammatory response in asthma." (PMID 35885021, 2022). "A signature containing CEACAM5 together with CD14 and TLR2 representing a response to bacterial infection has been described from an analysis of epithelial brushings and T‐cell transcriptomics from severe asthma patients." (PMID 35474304, 2022). "The anti-asthmatic effect of miR-224-5p in OVA-induced experimental asthma has been documented to be achieved by restricting pro-inflammatory TLR2 expression." (PMID 36184652, 2022). "Therefore, TLR2 could be linked to asthma severity through the IL-17 pathway." (PMID 33602227, 2021). "The correlation analysis results showed that CXCR1 (P = 0.02), CXCR2 (P = 0.02), and TLR2 (P = 0.01) were significantly related to asthma severity in GSE43696." (PMID 33602227, 2021).
asthma (continued). "Further studies showed that increased plant stanol consumption shifts T-cells towards a Th1 profile in asthma patients, a process likely mediated by TLR2 activation." (PMID 34066407, 2021). "Nevertheless, the relationship between CXCR1, CXCR2, TLR2 and asthma severity was stable, and combined hub genes were able to discriminate severe asthmatics from mild-moderate asthmatics in ROC analysis." (PMID 33602227, 2021). "The inhibition of miR-146a significantly reduced symptoms of asthma model with TLR2-related molecules being up-regulated." (PMID 32600285, 2020). "It was found that miR-146a is an important regulator in OVA-induced allergic asthma model, which can relieve symptoms of asthma through regulating TLR2 pathway." (PMID 32600285, 2020). "Regarding the combination of miR146a-inhibitor and miR146a-mimic, we also observed efficient anti-asthma effect, but the combination of miR146a mimic and Pam3CSK4 (TLR2 agonist) was the most efficient." (PMID 32600285, 2020). "miR-146a mimics attenuate allergic airway inflammation by impacting ILC2 via IRAK1/TRAF6 pathways, while miR-146a inhibitors attenuate asthma via activating TLR2-signaling pathways in inflammatory monocytes." (PMID 32600285, 2020). "It has been reported that two TLR2 single-nucleotide polymorphisms (SNPs) and four TLR4 SNPs significantly modified the effect of air pollution on the prevalence of doctor-diagnosed asthma from birth up to 8 years of age." (PMID 32411804, 2020). "Within the TLRs family, TLR2 is regarded as the major one responsible for the sustaining airway inflammation and thus be most relevant to the onset of asthma." (PMID 32117301, 2020). "Excitedly, several studies further indicated that activation of Toll-like receptors (TLRs) can effectively relieve asthma symptoms, and miR146a is upregulated by and negatively regulates TLR2 pathway in bacterial stimulation." (PMID 32600285, 2020). "Variant alleles of TLR2 and TLR4 genes also influenced the susceptibility to adverse effects of traffic-related air pollution on childhood asthma." (PMID 32411804, 2020). "In the experiment of OVA-induced allergic asthma model, it was found that miR-146a is an important regulator, which can regulate TLR2 pathway mediated by Th1 cytokines, thereby relieving symptoms of asthma." (PMID 32600285, 2020). "microRNA-146a has been reported to be a regulator in the process of attenuating asthma by inhibiting Toll-like receptor 2 (TLR2) pathway." (PMID 32600285, 2020). "ILC2 is differentiated from ILC3 in response to activation of TLR2 and produces IL-5 and IL-13, which plays vital role in initiating and promoting immune response among asthma patients, and leads to the accumulation of eosinophils in BALF." (PMID 32600285, 2020). "Genetic variation in TLR2 and TLR4 is a major determinant of susceptibility to asthma and allergy in rural children." (PMID 30140427, 2018). "We then analyzed the TLR2‐induced cytokine expression profile using PCR Array (Human Allergy & Asthma) and siRNA intervention." (PMID 30184256, 2018). "Apart from that, the anti-Th2 activity of TLR2 and 4 have received great of interest in the field of experimental asthma." (PMID 29867994, 2018). "TLR1, TLR2, TLR6, and TLR10 comprise the TLR2 subfamily, and TLR1, TLR2, TLR6, and TLR10 gene polymorphisms seem to play a role in susceptibility to asthma, atopic eczema, and allergic rhinitis." (PMID 28592890, 2017). "At present, any effect of the TLR2 and TLR4 gene polymorphisms on asthma is still largely undetermined." (PMID 28262750, 2017). "We have previously studied the TLR1 rs5743618, TLR2 rs5743708, and TLR6 rs5743810 polymorphisms and reported their associations with post-bronchiolitis asthma at preschool age10." (PMID 28592890, 2017). "Epidemiological studies have evaluated numerous polymorphisms in TLR2, TLR4 and CD14 in relation to asthma and similar phenotypes and some were significantly associated with high asthma prevalence, risk or severity." (PMID 27495363, 2016).
asthma (continued). "Other TLR2 SNPs have been associated with allergic asthma and TLR4 SNPs (Asp299Gly and T399I) with asthma pathogenesis in a German population." (PMID 27495363, 2016). "TLR2 and TLR4 are the most relevant to the onset of asthma and to the inflammatory responses underlying asthmatic exacerbations." (PMID 26617525, 2015). "Genetic variations in TLR1, TLR2, TLR4, TLR6 and TLR10 have been associated with the development of asthma." (PMID 24524443, 2014). "By contrast, the mucosal administration of a synthetic TLR2 agonist in the airways reliably reduced eosinophilia of the lungs in murine asthma models." (PMID 25309051, 2014). "Since we observe exacerbated asthma manifestations at this timepoint, it can be inferred that these TLR-2-expanded Treg cells displayed a reduced suppressive capacity." (PMID 23393567, 2013). "Nevertheless, from our data we cannot exclude that the expanding Tregs have bona fide suppressive activity, and are merely insufficient in number to functionally repress the TLR-2-induced exacerbated asthma manifestations." (PMID 23393567, 2013). "Here, we show that treatment of OVA sensitized mice with the TLR-2 agonist Pam3Cys induces a mild and transient exacerbation of asthma manifestations at the time of treatment." (PMID 23393567, 2013). "In mild asthma, Tlr2 expression was lower in sensitized only, challenged only and OVA-sensitized and challenged mice, when compared to the control mice." (PMID 23781124, 2013). "In severe asthma, allergen challenge only increased the expression of Tlr2 and allergen sensitization and challenge significantly increased Tlr1 expression when compared to sensitized only mice." (PMID 23781124, 2013). "In this respect, it has already been shown that in vitro TLR2 stimulation reduced the production of Th2 cytokines, that play an important role in asthma, via the upregulation of Th1 cytokine production." (PMID 23091602, 2012). "The majority of investigators examining the impact of genetics on responses to environmental microbial exposures in childhood asthma have focused on polymorphisms in CD14, TLR4, and TLR2." (PMID 22151743, 2011). "Mycoplasma infections prevent asthma, an effect which is partly dependent on the TLR2-IFN-γ -pathway." (PMID 18315836, 2008). "While murine models as well as epidemiological studies suggest an involvement of TLR4 agonists in modulating asthma or allergic diseases, TLR2 agonists can also decrease allergic immune responses in murine models." (PMID 16551363, 2006). "In the context of asthma, the role of TLR2 is particularly evident." (PMID 40672946, 2025). "Collectively, these studies suggest that TLR2 predominantly exerts a protective role in asthma." (PMID 40672946, 2025). "This highlights the importance of TLR2 in asthma pathogenesis." (PMID 40598285, 2025). "Furthermore, microRNA-146a (miR-146a), a key regulatory factor in ovalbumin (OVA)-induced allergic asthma models, alleviates asthma symptoms by modulating the TLR2 signaling pathway." (PMID 40672946, 2025). "However, further experimentation is required to confirm the direct regulatory effect of TLR2 on FcεRI expression in the context of asthma." (PMID 40672946, 2025). "Moreover, downregulation of GATA6 has been shown to reduce inflammation, infiltration, and mucus production by inhibiting TLR2 signaling in asthma models." (PMID 39897029, 2025). "Similarly, for TH2-associated autoimmune ailments such as asthma or atopic dermatitis, TLR1, TLR2, and TLR6 antagonists offer treatment avenues." (PMID 37760825, 2023). "In particular, single nucleotide polymorphism (SNP) alleles in the transient receptor potential ankyrin 1 (TRPA1), transient receptor potential vanilloid (TRPV1), toll-like receptor 2 (TLR2) and toll-like receptor 4 (TLR4) have been associated with asthma susceptibility and symptom severity 3–7." (PMID 37679687, 2023).
asthma (continued). "Other asthma controllers include immune modulators such as immune suppressors (methotrexate and cyclosporine A) and immune potentiators (glucocorticoids, 1,25-dihydroxy vitamin D3, and toll-like receptor 2/4/9 ligands)." (PMID 37569846, 2023). "Furthermore, hub genes, such as CXCR1, CXCR2, and TLR2, were identified as biomarkers of asthma severity through either the neutrophil inflammation pathway or Th17 immune pathway." (PMID 33602227, 2021). "One line of inquiry could examine the possibility that TLR10 dampens TLR2 signaling and IL6 production, thereby increasing the risk of asthma." (PMID 34103634, 2021). "Furthermore, when compared with mild asthmatics in our study, severe asthmatics also showed upregulated TLR2, highlighting the role of TLR2 on asthma progression." (PMID 33602227, 2021). "Another study in mice also suggested that appropriate stimulation of the TLR2/4 pathway may help to prevent asthma in offspring." (PMID 33602227, 2021). "Our previous report suggested that TLR2 knockout in mice alleviated asthma." (PMID 34315511, 2021). "TLR2 probably take part in asthma progression by inducing Th17 responses and production of IL-8 and IL-17, which could modify airway structures, leading to airway obstruction and low FEV1 seen in patients with severe asthma." (PMID 33602227, 2021). "TLR2 and TLR4 polymorphisms were associated with various conditions such as asthma, pulmonary tuberculosis, Helicobacter pylori infection, as well as alterations in levels of high-density lipoprotein cholesterol, low-density lipoprotein cholesterol and triglycerides." (PMID 34441346, 2021). "To date, TLR2 has been considered as the most relevant to the onset of asthma." (PMID 32117301, 2020). "Future work and direction would ideally see the development of a suitable candidate for administration in humans, and it is possible that TLR2 agonists currently used therapeutically such as OK-432 for cancer, may be viable treatments for AR and asthma." (PMID 33281825, 2020). "For instance, some studies with TLR1 or TLR2 agonists suggested that their activation results in asthma inhibition, while other studies indicated that activation of these receptors could promote allergic asthma." (PMID 29867994, 2018). "However, a study demonstrated that activation of the TLR2/NLRP3/IL‐18 axis can protect against asthma 3, complicating the role of IL‐18 in asthma." (PMID 28922563, 2018). "However, the relationship between B7-H3 and TLR2 in pathogenisis of asthma has not been fully understood." (PMID 28094276, 2017). "Therefore, we investigated the effect of a preventative treatment with combinations of Tlr1, Tlr2 and Tlr6 mRNA in a House Dust Mite-induced mouse model of asthma." (PMID 27101288, 2016). "In fact, we found the TLR2 +596 SNP to be associated to asthma in Puerto Ricans, but others did not obtain any association with asthma in farmers/non-farmers European children." (PMID 27495363, 2016). "It has remained elusive whether the toll-like receptors (TLR2)/mycloid differentiation factor 88 (MyD88)/nuclear factor (NF)-κB signaling pathway is involved in lipoxin A4 (LXA4)-induced protection against asthma." (PMID 25760938, 2015). "In addition, activation of TLR2 induced a T helper type 2 immune response and promoted experimental asthma." (PMID 25760938, 2015). "When macrophages are deficient in gal-3 there is increased responses to LPS, reduced bacterial replication and increased expression of IL-1β, TLR2 and IL-6, which are similar observations to those we have previously reported in patients with the neutrophilic subtype of asthma and COPD." (PMID 25616863, 2015). "TLR2 promotes Th2-biased immune responses, which may be correlated to the Th1/Th2 imbalance in asthma." (PMID 26617525, 2015).